MTA2 (metastasis associated 1 family member 2)
Description:
May function as a transcriptional coregulator. Acts as a component of the histone deacetylase NuRD complex which participates in the remodeling of chromatin.
Synonyms: MTA1L1; PID; MTA1-L1
Tractability: PROTAC: UniProt records ubiquitination sites on it; ubiquitination databases record sites on it; its protein half-life has been measured.
Gene: Protein-coding gene on chromosome 11 (62,593,214 to 62,601,865, reverse strand). Ensembl gene ENSG00000149480.
Subcellular location: Nucleus
Subcellular location (Human Protein Atlas): Nucleoplasm
Pathways (Reactome):
Gene expression (Transcription): ERCC6 (CSB) and EHMT2 (G9a) positively regulate rRNA expression; RNA Polymerase I Transcription Initiation; Regulation of endogenous retroelements by KRAB-ZFP proteins; Regulation of endogenous retroelements by Piwi-interacting RNAs (piRNAs)
Chromatin organization: HDACs deacetylate histones; Interaction of NuRD complexes with transcription factors; NuRD complex assembly
Developmental Biology: Differentiation of naive CD4+ T cells to T helper 2 cells (Th2 cells); Transcriptional regulation of brown and beige adipocyte differentiation by EBF2
Disease: Potential therapeutics for SARS
Signal Transduction: Regulation of PTEN gene transcription
Gene Ontology:
Molecular function: nucleosomal DNA binding; protein binding; RNA polymerase II-specific DNA-binding transcription factor binding; histone deacetylase binding; transcription coactivator activity; transcription corepressor activity; chromatin binding; DNA-binding transcription factor binding; histone deacetylase activity; sequence-specific DNA binding; transcription coregulator activity
Biological process: chromatin remodeling; chromatin organization; negative regulation of DNA-templated transcription; negative regulation of transcription by RNA polymerase II; positive regulation of DNA-templated transcription; regulation of cell fate specification; regulation of stem cell differentiation; regulation of DNA-templated transcription; regulation of fibroblast migration
Cellular component: chromatin; chromosome, telomeric region; membrane; nucleoplasm; nucleus; NuRD complex; protein-containing complex; transcription regulator complex; histone deacetylase complex
Genetic constraint (gnomAD): Loss-of-function variants: 22 observed, 90.15 expected, observed/expected ratio (o/e) 0.24, 90% interval 0.17 to 0.35. The upper end of that interval is the gene's LOEUF score, 0.35, which puts it in group 1 of 6, group 1 being the genes least tolerant of losing a copy. Missense variants: 542 observed, 893.01 expected, observed/expected ratio (o/e) 0.61, 90% interval 0.56 to 0.65. Synonymous variants: 314 observed, 325.69 expected, observed/expected ratio (o/e) 0.96, 90% interval 0.88 to 1.06.
Homologues: Orthologues: rabbit MTA2 (99% identical), chimpanzee MTA2 (99% identical), dog MTA2 (99% identical), macaque MTA2 (99% identical), mouse Mta2 (99% identical), rat Mta2 (98% identical), guinea pig MTA2 (98% identical), pig MTA2 (98% identical), tropical clawed frog mta2 (90% identical), zebrafish mta2 (75% identical), Drosophila melanogaster MTA1-like (50% identical). Paralogues in human: MTA1 (63% identical), MTA3 (57% identical), MIER3 (16% identical), MIER2 (14% identical), MIER1 (14% identical).
Diseases named in the same sentence as MTA2 in open-access papers:
MTA2 is named in the same sentence as 69 diseases in open-access papers, as found by Europe PMC text mining. Sharing a sentence is not in itself a finding about the gene and the disease. The quoted sentences say what the papers report.
gastric cancer (25 papers, 2013 to 2026). A primary or metastatic malignant neoplasm involving the stomach. "SNHG5, the host gene of snoRNA U50, inhibits gastric cancer progression by sequestering metastasis-associated protein 2 (MTA2) in the cytoplasm, indicating its therapeutic value in gastric cancer." (PMID 41019058, 2025). "Metastasis-associated tumor gene family 2 (MTA2) and transcription factor specificity protein 1 (Sp1) expression were detected in 127 gastric cancer samples by immunohistochemistry staining." (PMID 24010737, 2013). "MTA2 gene belongs to metastasis associated family, and is highly expressed in some solid tumors, including gastric cancer." (PMID 24010737, 2013). "A recent study conducted by a team of researchers at Beijing Proteome Research Center found that metastasis-associated protein 2 (MTA2), which associates with replication origins and compounds the replication stress induced by Olaparib, was found in high levels among gastric cancer tumors." (PMID 37508568, 2023). "In contrast to its EMT-promoting role in CRC and HCC, SNHG5 has been reported to suppress EMT in gastric cancer by binding and retaining MTA2 in the cytoplasm, thereby inhibiting NuRD complex–mediated chromatin remodeling." (PMID 41550840, 2026). "It has also been demonstrated that the reduction in miR-1236 suppression effect by targeting MTA2 expression promotes gastric cancer progression." (PMID 41009512, 2025). "Our previous study has reported that metastasis-associated protein 2 (MTA2) plays essential roles in tumorigenesis and aggressiveness of gastric cancer (GC)." (PMID 38474064, 2024). "MTA2 expression is regulated by the transcription factor Sp1 in gastric cancer and is capable of promoting the migration and invasion of gastric cancer cells." (PMID 37371463, 2023). "Studies have confirmed that miR-1236-3p can inhibit the invasion and proliferation of gastric cancer cells by inhibiting the expression of MTA2." (PMID 35484118, 2022). "In gastric cancer, SP1 binds to the MTA2 gene promoter, up‐regulates MTA2 gene expression, and facilitates gastric cancer cell invasion and migration." (PMID 34185412, 2021). "But SNHG5 was found to be downregulated in gastric cancer and blocked gastric cancer progression by trapping MTA2." (PMID 32131767, 2020). "In gastric cancer, MTA2 can be transcriptionally regulated by specificity protein 1 (Sp1), and MTA2 expression is closely related to tumour invasion, lymph node metastasis, and Tumor-Node-Metastasis (TNM) staging." (PMID 31771219, 2019). "A study also revealed that SNHG5 suppresses gastric cancer progression by trapping MTA2 in the cytosol." (PMID 30764831, 2019). "The result showed that MTA2 level in gastric cancer tissues were higher than that in adjacent tissues." (PMID 29743816, 2018). "Long non-coding RNA SNHG5 also suppresses gastric cancer progression by trapping MTA2 in the cytosol, in addition to being a new biomarker in malignant melanoma." (PMID 30250399, 2018). "Herein, we found that MTA2 overexpression in gastric cancer increased colony formation in vitro and tumor growth in vivo, including either subcutaneous xenografts or pulmonary metastases." (PMID 25929737, 2015). "In present study, to validated MTA2 biological function, MTA2 overexpression cell models established by MTA2 low expression gastric cancer cells were investigated." (PMID 25929737, 2015). "In present study, IL-11 expression was found related with MTA2 in gastric cancer cells by genome expression analysis, and was validated in both cell models and xenografts tissues." (PMID 25929737, 2015). "We have previously reported that MTA2 knockdown in SGC-7901 and AGS gastric cancer cell lines with high MTA2 expression inhibited gastric cancer cell invasion and metastasis." (PMID 25929737, 2015). "MTA2 overexpression models were established by transfection assay in gastric cancer cells BGC-823 and MKN28." (PMID 25929737, 2015).
gastric cancer (continued). "We have preliminarily reported MTA2 expression in gastric cancer and its biological functions by using knockdown cell models, while the molecular mechanisms of MTA2 in regulating malignant behaviors are still unclear." (PMID 25929737, 2015). "We have previously reported that MTA2 gene was overexpressed in gastric cancer tissues, correlating with tumor invasion, lymph node metastasis, and advanced TNM stage." (PMID 25929737, 2015). "MTA2 protein was mainly localized in the nuclear of gastric cancer cells, and its expression was much more dominant in tumor tissues than that in neighboring gastric mucosa." (PMID 24010737, 2013). "MTA2 expression in gastric cancer cell lines SGC-7901 and AGS was knocked down by shRNA transfection, and cells transfected by vector was identified as negative control." (PMID 24010737, 2013). "MTA2 knockdown didn’t interfere gastric cancer cell growth in proliferation assay, but colony formation was attenuated." (PMID 24010737, 2013). "The results of present study revealed the role of MTA2 in regulating gastric cancer cell mobility and invasion." (PMID 24010737, 2013). "MTA2 expression was positively correlated with transcription factor Sp1 in gastric cancer tissues (r = 0.326, P < 0.001)." (PMID 24010737, 2013). "In present study, the biological function of MTA2 protein in gastric cancer was assessed both in vitro and in vivo, the role of Sp1 in transcriptional regulation of human MTA2 gene promoter was also investigated." (PMID 24010737, 2013). "The expression rate of MTA2 in gastric cancer tissues was 55.9% (71/127), and its expression was closely related to the depth of tumor invasion, lymph nodes metastasis, and TNM staging." (PMID 24010737, 2013). "The results of this study validated the patterns of MTA2 expression in gastric cancer tissues as we previously reported." (PMID 24010737, 2013). "In conclusion, aberrant expression of MTA2 in gastric cancer cells participates in cell mobility and invasion." (PMID 24010737, 2013). "SGC-7901 and AGS gastric cancer cell lines transfected by MTA2 shRNA was used for biological function investigation." (PMID 24010737, 2013). "Sp1 was found to be overexpressed in gastric cancer tissues, and had positive correlation with MTA2." (PMID 24010737, 2013). "The results of immunohistochemistry staining revealed that, the positive rate of MTA2 protein in gastric cancer tissues was 55.9% (71/127)." (PMID 24010737, 2013). "MTA2 knockdown impairs invasion and metastasis of gastric cancer cells, and attenuates xenografts growth in vivo." (PMID 24010737, 2013). "DNA replication may be associated with E2F2, according to research, which shows that MTA2 impairs DNA replication stress in gastric cancer cells and increases their sensitivity to PARP inhibition." (PMID 36923953, 2023). "In summary, our study found that H. pylori could upregulate the expression of circMAN1A2 and affect the occurrence and development of gastric cancer by regulating the circMAN1A2-miR-1236-3p-MTA2 axis." (PMID 35484118, 2022). "The downregulation of circMAN1A2 could inhibit the proliferation, migration and invasion of gastric cancer cells, and circMAN1A2 could promote the progression of gastric cancer induced by H. pylori by sponging miR-1236-3p to regulate MTA2 expression." (PMID 35484118, 2022). "In addition, metastasis associated protein 2 (MTA2) is an metastasis-associated gene, and its lncRNA MTA2TR was overexpressed in gastric cancer and pancreatic cancer." (PMID 33109235, 2020). "IL-11 is one of the downstream effectors of MTA2 in regulating gastric cancer cells growth." (PMID 25929737, 2015). "The rescue assay suggested that MTA2 promoting gastric cancer cell colony formation might partially through IL-11 as a downstream effector." (PMID 25929737, 2015).
gastric cancer (continued). "Changes of cells morphology and reduced CD24 and MYLK expression further supported the conclusion that depression of cell mobility could be the major consequence of MTA2 knockdown in gastric cancer cells." (PMID 25929737, 2015). "MTA2 knockdown significantly inhibited gastric cancer cell invasion and metastasis." (PMID 25929737, 2015). "Overexpression of Sp1 could regulate the transcriptional activity of MTA2 promoter and might partially contribute to MTA2 expression in gastric cancer." (PMID 24010737, 2013). "Concomitant expression of MTA2 and Sp1 was also observed in gastric cancer cell lines." (PMID 24010737, 2013). "The impacts of MTA2 knockdown on gastric cancer cell growth in vitro seemed to be a paradox." (PMID 24010737, 2013). "Both MTA2 and Sp1 protein had similar expression pattern in gastric cancer tissues." (PMID 24010737, 2013). "Attenuation of tumorigenesis and metastasis in vivo validated the result of colony formation assay, indicated that MTA2 knockdown could impair the anchorage-independent growth of gastric cancer cells." (PMID 24010737, 2013). "In this study, we found that knockdown of MTA2 gene expression could alter gastric cancer cell morphology and disturb F-actin structure." (PMID 24010737, 2013). "H. pylori-circMAN1A2-miR-1236-3p-MTA2, a new signalling cascade, provides novel research ideas for clarifying the oncogenic mechanism of H. pylori and provides an experimental basis for exploring the molecular mechanism by which circMAN1A2 promotes the occurrence and development of gastric cancer." (PMID 35484118, 2022). "Concomitant expression of MTA2 and Sp1, and high GC-content sequence in proximal region of human MTA2 promoter, the potential Sp1 binding region, indicated that MTA2 might also be a downstream gene of Sp1 in gastric cancer." (PMID 24010737, 2013). "Whether MTA2 could be served as a prognostic factor of gastric cancer was still unclear." (PMID 24010737, 2013). "MTA2 has been linked to tumour invasion depth, regional lymph node metastasis, distant metastasis, and poor long-term survival rates independent of age or gender in patients with esophageal squamous cell carcinoma, gastric cancer, non-small-cell lung cancer, and colorectal cancer." (PMID 31771219, 2019). "For example, Sp1 positively regulates MTA2 and midkine (MDK) expressions in gastric cancer tissues 30 and glioma cells 29, respectively." (PMID 26763486, 2016). "MTA2 knockdown in human SGC-7901 and AGS gastric cancer cells significantly inhibited migration and invasion in vitro, and disrupted structure of cytoskeleton." (PMID 24010737, 2013). "MTA2 overexpression enhances colony formation and tumor growth of gastric cancer cells, but does not promote tumor migration and metastasis." (PMID 25929737, 2015). "MTA2 overexpression enhances colony formation and tumor growth of gastric cancer cells, but not plays important role in cancer cell migration and metastasis." (PMID 25929737, 2015). "MTA2 participated in gastric cancer cell invasion, but might not be a dominant regulator." (PMID 25929737, 2015).
breast carcinoma (20 papers, 2011 to 2025). "It has been demonstrated that MTA2 is associated with aggressive malignant phenotypes of numerous cancers such as breast cancer, hepatocellular carcinoma, and PDAC29." (PMID 30814496, 2019). "In addition, whether the interaction of NE with MTA2 is associated with its malignant roles in breast cancer and in what circumstances NE promotes or inhibits breast cancer metastasis remain interesting questions that require further exploration." (PMID 30642362, 2019). "TTC39A-AS1 was shown to function as a competing endogenous RNA, sponging miR-483-3p to upregulate MTA2 in breast cancer, thereby promoting tumorigenicity." (PMID 39697329, 2024). "For example, lncRNA TC39A-AS1 acts as a competing endogenous RNA in breast cancer by sponging miR-483-3p, indirectly increasing MTA2 expression and tumorigenicity of breast cancer." (PMID 36980601, 2023). "This breast cancer cell line is often associated with metastasis-associated proteins (MTA) MTA1 and MTA2 that depict overexpression or reduced expression to contribute to the metastasis of the ZR-75-30 breast cancer cell line." (PMID 38137912, 2023). "Estrogen dependent interaction between AIB1 and MTA2 have previously been identified in screening studies in endocrine sensitive breast cancer cells, although the mechanism of action in the context of endocrine resistant tumors has not been described." (PMID 33420368, 2021). "As the first member of the metastasis-associated protein (MTA) family, MTA1 and another MTA family member, MTA2, have both been reported to promote breast cancer progression and metastasis." (PMID 30642362, 2019). "The overexpression of MTA1 has been shown to downregulate the expression of MTA2 at the protein level instead of by transcriptional repression in breast cancer cells." (PMID 30642362, 2019). "Transwell assays were used to assess the roles of MTA1 and MTA2 in the metastasis of ZR-75-30 luminal B breast cancer cells in vitro." (PMID 30642362, 2019). "MTA1 and MTA2 play opposing roles in the metastasis of ZR-75-30 luminal B breast cancer cells in vitro." (PMID 30642362, 2019). "Overall, our study provided direct evidence for the different roles that MTA1 and MTA2 play in breast cancer cell metastasis and clarified the mechanism by which MTA1 downregulates MTA2 at the protein level." (PMID 30642362, 2019). "We further identified that the TP63 gene was repressed by this precision-guided machinery of TRPS1-CHD4/NuRD(MTA2) complex, which decommissions its enhancer leading to a decrease in ΔNp63 and enhancing the metastatic ability of breast cancer cells." (PMID 30563971, 2018). "Nevertheless, our identification of TRPS1-CHD4/NuRD(MTA2) complex-regulated genes, which are enriched in cell adhesion and cell migration pathways, provides additional support and mechanistic insight into breast cancer metastasis." (PMID 30563971, 2018). "Taken together, our results suggested that elevated expression of TRPS1 nucleates CHD4/NuRD(MTA2) complex to repress ΔNp63 expression to reduce cell migration and invasion of breast cancer cells and better survival." (PMID 30563971, 2018). "MTA2 over-expression in ERa-positive breast cancer cells resulted in an enhanced anchorage-independent growth." (PMID 29743816, 2018). "On the other hand, in mouse breast cancer 4 T1 cells and glioma cells, it was reported that MTA2 knockdown impaired cell invasion and metastasis." (PMID 25929737, 2015). "MTA2 is a corepressor of ERα and increased MTA2 expression leads to estrogen-independent growth of mammary carcinoma cells during mammary carcinoma progression and metastasis." (PMID 22060274, 2011).